ALK (ALK receptor tyrosine kinase)
Diseases named in the same sentence as ALK in open-access papers (continued):
Sharing a sentence is not in itself a finding about the gene and the disease.
lung cancer (continued). "The EML4‐ALK fusion was shown to be variant 1 via comparative western blotting of the same variant harbored by the commonly used ALK‐rearranged lung cancer cell line NCI‐H3122." (PMID 36423211, 2023). "These animal models are valuable as they exhibit sensitivity to ALK inhibition, allowing for the exploration of the mechanisms underlying EML4–ALK‐induced lung cancer and the evaluation of ALK‐targeted therapy's effectiveness." (PMID 38077251, 2023). "The other is the EV blood test kit ExoDx Lung (ALK) for detecting EML-4-ALK mutations in patients with nonsmall cell lung cancer (NSCLC)." (PMID 37456240, 2023). "The miRNA expression profile of lung tumors with ALK rearrangements was distinct from lung cancers with EGFR and KRAS mutations." (PMID 36821071, 2023). "Among these, 25% of lung cancer patients develop ALK-rearranged mutations and 33% of patients develop activating mutations." (PMID 37835467, 2023). "The precision treatment of patients with lung cancer was decided based on their tatus of the ALK gene mutation, detected via sequencing of their cognate CTC DNA content." (PMID 37371825, 2023). "We have presented data on testing and treatment patterns of EGFR- and ALK-mutated lung cancer on a national level." (PMID 36900294, 2023). "We elucidated molecular mechanisms underlying STAT3-mediated adaptive survival of ALK-rearranged lung cancer cells." (PMID 35228642, 2022). "The same procedure was used to expand CTCs from a single patient with ALK-positive lung cancer to estimate in real time the drug resistance profile caused by the ALK rearrangement by testing different drugs in vitro." (PMID 35484215, 2022). "A recent study found that ALK inhibitors can increase the dosage of HLA associated proteins on the surface of ALK mutated lung cancer cells in both in vitro and in vivo experiments, while they can decrease PD-L1 levels on the surface of tumor cells by 75%." (PMID 36591504, 2022). "Information about the incidence of hippocampal BM according to the lung cancer stage or EGFR/ALK mutation status can serve as a good guide for the indication for HA-WBRT." (PMID 35619920, 2022). "In conclusion, we present a case of advanced lung cancer with ALK mutation during long-term immunosuppressive treatment for RA-OP." (PMID 36626420, 2022). "Except in a few cases, tumors with EGFR or ALK mutations showed a linear connection between 22C3 and SP263, which is likely attributable to high levels of PD-L1 expression in lung cancer samples with driver mutations like EGFR or ALK mutations." (PMID 35804910, 2022). "We next explored the molecular mechanisms underlying STAT3-mediated adaptive survival of ALK-rearranged lung cancer cells by DNA microarray analysis in YHO-1701-treated cells." (PMID 35228642, 2022). "The reason for this problem is that only 35–36% of lung cancer patients are caused by ALK gene mutations, which means that the ceritinib capsule is only effective for one subtype of lung cancer." (PMID 35711917, 2022). "Providers’ confidence was correlated with the availability of in-house genomic testing, more than 10 years of oncology experience, and high volumes of patients with lung cancer in general, and patients with EGFR-mutated and ALK-rearranged lung cancer." (PMID 36193188, 2022). "Anaplastic lymphoma kinase (ALK)‐rearrangement (also known as ALK fusion) accounts for 3%–11% in non‐small cell lung cancer (NSCLC) which is the leading cause of cancer‐related death in China and worldwide." (PMID 35616090, 2022). "To explore the molecular mechanisms underlying treatment-induced adaptive survival of ALK-rearranged lung cancer cells, we performed functional genomic CRISPR KO screen using small guide RNA (sgRNA) libraries." (PMID 35228642, 2022). "Third, Wt patients are a heterogeneous population that includes patients with KRAS, ALK, and ROS-1 mutation lung cancer." (PMID 36085020, 2022).
lung cancer (continued). "For example, epidermal growth factor receptor (EGFR) mutations and ALK rearrangements are usually indicative of a lung cancer origin (most CUP cases), while BRAF and NRAS mutations are associated with melanoma." (PMID 35225863, 2022). "EML4 is currently receiving attention due to its possible fusion with anaplastic lymphoma kinase (ALK) forming pathological EML4-ALK variants associated with lung cancer." (PMID 35478957, 2022). "Targeted therapeutic drugs such as anaplastic lymphoma kinase (ALK) inhibitors and epidermal growth factor receptor (EGFR) inhibitors have showed a promising performance in clinical trials for treating lung cancer patients with ALK or EGFR mutations." (PMID 35801241, 2022). "ALK is a recognized molecular target in a variety of ALK mutated malignancies, including non–small cell lung cancer." (PMID 35956900, 2022). "Based on this first report of BRAF A598-T599insV mutation occurring in lung cancer, we discuss resistance mechanisms to ALK TKIs, implications of BRAF mutation in NSCLC, and BRAF A598-T599insV mutation in other cancers." (PMID 36419902, 2022). "ALK was first described as an oncogene, and several of its mutations have been linked to tumorigenesis, including neuroblastomas and non–small cell lung cancer, highlighting its importance in cancer biology." (PMID 35608912, 2022). "Although molecular targeted therapy against mutated driver oncogene such as EGFR or ALK has improved the survival rates of patients with lung cancer, BMs remain an important cause of morbidity and are associated with progressive neurologic deficits." (PMID 35619920, 2022). "In lung cancer, for example, YAP1 activation confers resistance to therapies targeted against common lung cancer oncogenes, such as anaplastic lymphoma kinase (ALK), BRAF or mutated epidermal growth factor receptor (EGFR) tyrosine kinase." (PMID 34685695, 2021). "In the current study, our data revealed 98 (56.7%) EGFR mutations in 173 patients with lung cancer and 14 (2.7%) ALK fusions in 521 patients." (PMID 34234236, 2021). "In cancers driven by ALK fusions such as EML4(Echinoderm microtubule-associated protein-like 4)-ALK(+) lung cancer, ALKi+RAFi+MEKi+ERKi treatment was very effective in suppressing tumor cell growth." (PMID 34461089, 2021). "Three major variants (v1: E13;A20, v2: E20;A20, and v3: E6;A20) account for more than 90% of lung cancers patients with fusion of ALK and EML-4 (Echinoderm Microtubule-Associated Protein-Like 4) genes." (PMID 34686712, 2021). "Here, the authors show the multi-kinase inhibitor gilteritinib is effective against different mutations that arise during lorlatinib in ALK fusion positive lung cancer to cause resistance." (PMID 33627640, 2021). "The role of EMT biomarkers FN1 and VIM and the matric metalloproteinases, MMP-9 and MMP-7, in lung cancer in the background of ALK mutation is under study." (PMID 33091333, 2021). "Among the 5 ALK-positive cases with lung cancer, the following variants were identified: three (60%) exhibited EML4-ALK-V3a fusion (cases 3, 4 and 5), one (20%) exhibited EML4-ALK-V5p fusion (case 5) and two (40%) exhibited EML4_ex13 fusion (cases 1 and 2)." (PMID 34234236, 2021). "Along the same lines, YAP1 activation was associated with poor response to treatment with the ALK/ROS1 inhibitor crizotinib in ALK-rearranged lung cancers." (PMID 34685695, 2021). "Anaplastic lymphoma kinase (ALK) rearrangement is the second most common driver mutation found in lung cancer, and several ALK inhibitors have shown excellent efficacy." (PMID 33921762, 2021). "ctDNA testing has been indicated to be effective in identifying both ALK point mutations and fusions in lung cancer patients, who will most likely to respond to crizotinib and other ALK tyrosine kinase inhibitors." (PMID 34422670, 2021).
lung cancer (continued). "In our study, we measured the frequency of EGFR and ALK concurrent mutations associated with lung cancer, and studied the responses to TKI treatment in this rare patient population." (PMID 34654390, 2021). "The echinoderm microtubule-associated protein-like 4 (EML4)-anaplastic lymphoma kinase (ALK) fusion gene, a driver mutation in lung carcinoma, is fairly common in lung adenocarcinoma but rare in large cell neuroendocrine carcinoma (LCNEC)." (PMID 34377493, 2021). "In fact, FISH, IHC or RT-PCR can be used as diagnostic techniques for ALK-positive lung cancer, which is recommended by the Diagnostic and Therapeutic Guidelines for Primary Lung Cancer of the Chinese Society of Clinical Oncology." (PMID 32047559, 2020). "A recent study of young patients with nonsmall cell lung cancer showed that higher frequency of ALK and HER2 genetic alterations were associated with young age, while, mutations in KRAS, STK11, and EGFR exon 20 are more common in older patients." (PMID 32657049, 2020). "This likely relates in part to delays in diagnosis and higher frequencies of driver mutations (e.g., EGFR and ALK mutations in lung cancer patients)." (PMID 33218178, 2020). "The goals of this study were to assess the frequency and potential causes of inconsistent ALK FISH results in consecutive samples of patients with lung cancer." (PMID 32674491, 2020). "In accordance with ALK fusions in lung cancer, the phenomenon of dual driver mutations and gene fusions has also been detected and elucidated in the never smoking patients with NSCLC (mainly lung adenocarcinomas) in several studies." (PMID 33520689, 2020). "The treatment options for EGFR-mutated and ALK-rearranged NSCLCs are distinctly different from those of lung cancer that lacks actionable mutations." (PMID 32030321, 2020). "The aim of this study was to better understand the frequency and causes of inconsistent ALK FISH results in lung cancer patients." (PMID 32674491, 2020). "Since ALK fusion is a rare mutation in lung cancer, it would be worthwhile to explore the real-world conditions in different institutes." (PMID 33273548, 2020). "Most unique to lung cancer is a fusion between ALK and the microtubule associated protein like 4 EML4." (PMID 32283832, 2020). "The anaplastic lymphoma kinase (ALK) fusion has been identified to be a driver gene in lung cancer, and serves as important diagnostic and therapeutic targets." (PMID 33157918, 2020). "Anaplastic lymphoma kinase (ALK) fusion mutations are validated molecules targeted therapy in lung cancers, where crizotinib can be used as the specific inhibitor to suppress tumor progression." (PMID 32164629, 2020). "Research involving lung cancer genotyping for other mutations, such as rearrangements in ALK, ROS1, or RET genes, amplifications in the MET gene, or mutations in the BRAF or HER2 genes, has started to slowly develop." (PMID 31818027, 2019). "It is well acknowledged in ALK mutated lung cancer the occurrence of mutations in the tyrosine kinase domain, for example L1196M and C1156Y, upon treatment with crizotinib." (PMID 31795465, 2019). "Tyrosine kinase inhibitors (TKIs) can significantly prolong overall survival for patients with advanced non‐small cell lung cancer (NSCLC) harboring epidermal growth factor receptor (EGFR)‐mutation or anaplastic lymphoma kinase (ALK)‐rearrangement." (PMID 31144459, 2019). "The identification of inversions of echinoderm microtubule-associated protein-like 4 (EML4) with ALK in Japanese women with lung cancer led to the development of drugs targeting EML4-ALK fusions." (PMID 30886831, 2019).
lung cancer (continued). "Since the cribriform pattern is closely associated with ALK-positive lung cancer, it was difficult to accurately determine which factors, predominantly contributed to the statistical significances." (PMID 31561631, 2019). "Patients with non‐small cell lung cancer (NSCLC) harboring the echinoderm microtubule‐associated protein‐like 4 (EML4)–ALK fusion exhibit remarkable initial responses to ALK‐TKIs." (PMID 31633304, 2019). "The fusion between echinoderm microtubule-associated protein-like 4 (EML4) gene and ALK (EML4-ALK) was the first fusion oncogene detected in lung cancer." (PMID 31795465, 2019). "The ROS1 G2032R mutation is analogous to the ALK G1202R mutation identified in crizotinib-, ceritinib-, and alectinib-resistant ALK-rearranged lung cancers." (PMID 31399568, 2019). "With the development of next-generation sequencing, more ALK fusion variants can be found, and the entire picture of ALK fusion lung cancer will become clearer." (PMID 31608224, 2019). "The development of PEM resistance in lung cancer with an ALK rearrangement is associated with the activation of the EGFR-HER family, which provides a rationale for the use of the pan-her inhibitor, afatinib, to overcome PEM-acquired resistance." (PMID 31795298, 2019). "Mutations in epidermal growth factor receptor (EGFR), and rearrangements of anaplastic lymphoma kinase (ALK) are targetable in lung cancer, while BRAF mutations have been successfully targeted in metastatic melanoma." (PMID 30886831, 2019). "KIT amp, EGFR amp, MET amp and ALK mutation in lung cancer, and CCNE1 amp in breast cancer were curated as resistant information only in the QCII." (PMID 31383922, 2019). "Three generations of ALK inhibitors have been developed for the treatment of non–small cell lung cancer with certain mutations in Alk." (PMID 31031625, 2019). "ALK-related mutations, which are well known in lung cancer as noted in the Introduction, are also seen in rhabdomyosarcoma, especially in the alveolar type; an ALK gene copy number gain is detected in the vast majority of alveolar rhabdomyosarcomas." (PMID 30487384, 2018). "Specific tyrosine kinase inhibitors have shown remarkable clinical response in patients with tumors characterized by RTK activation, such as gefitinib and erlotinib in EGFR-mutated and crizotinib in ALK- or ROS1-rearranged lung cancer." (PMID 29755689, 2018). "McCoach and colleagues are implementing a clinical trial (NCT03088930) in which patients with early stage lung cancers bearing activating mutations in ALK, ROS1 or MET exon 14 are treated with neoadjuvant crizotinib." (PMID 29458371, 2018). "Prior meta-analyses in lung cancer have shown decreased response to ICI in EGFR or ALK mutant subgroups, while BRAF mutations in melanoma have shown the opposite effect." (PMID 29743104, 2018). "In order to identify genes (and pathways) whose suppression can confer sensitivity to crizotinib, we used a loss-of-function genetic screen in ALK rearranged lung cancer cell lines." (PMID 29507657, 2018). "The anaplastic lymphoma kinase (ALK) is a receptor tyrosine kinase encoded by the ALK gene localized on chromosome 2 and is often associated with lung cancer when mutated." (PMID 29973561, 2018). "We have learned, for instance, that neuroblastoma bearing activating anaplastic lymphoma kinase (ALK) mutations respond much less efficiently upon crizotinib treatment than ALK translocations in lymphoma or lung cancer." (PMID 30171420, 2018). "The use of ALK-TKIs significantly increases the risk of developing all-grade and high-grade liver toxicities in lung cancer patients." (PMID 29507704, 2018). "With regards to lung cancer, the H2228 and H3122 human lung cancer cell lines are EML4-ALK-positive (though they carry different variants) and have been widely used to dissect ALK signaling." (PMID 29455675, 2018).
lung cancer (continued). "The echinoderm microtubule-associated protein-like 4 (EML4)-ALK fusion protein was the first reported oncogenic kinase in lung cancer and is located on chromosome 2." (PMID 29435193, 2018). "Overexpression of miR-1343-3p and reduced expression of miR-671-3p, miR-103a-3p, let-7e, and miR-342-3p were especially distinctive in the ALK-rearranged lung cancer compared with EGFR-mutated and KRAS-mutated lung cancer." (PMID 29189709, 2017). "In current clinical trials of lung cancer immune checkpoint blockade treatment, patients with ALK fusion and EGFR mutation have shown minimal responses." (PMID 29189709, 2017). "EGFR mutations or ALK rearrangements in lung cancer, BRAF V600E mutations in metastatic melanoma and breast cancer patients harbouring HER2 amplifications are examples of therapeutic biomarkers routinely used in the adult population." (PMID 29340109, 2017). "Among the most abundant are fusions of the ALK gene with portions of the gene encoding the echinoderm microtubule-associated protein-like 4 (EML4) in lung cancer." (PMID 29189709, 2017). "Other prognostic and predictive markers include estrogen receptor (ER)/progesterone receptor (PR)/human epidermal growth factor receptor 2 (HER2) for breast cancer, KRAS mutation for colon cancer, and anaplastic lymphoma kinase (ALK) mutation for lung cancer." (PMID 28335509, 2017). "MiR-660-5p can not only be used as a diagnostic marker for ALK-positive lung cancer, but is also associated with the efficacy of crizotinib." (PMID 28514730, 2017). "Chromosomal rearrangements of ALK have been found to be associated with lung cancer and its inhibitors ceritinib are superior for patients with chemotherapy." (PMID 28615068, 2017). "increased signalling via signal transducer and activator of transcription 3 (STAT3), extracellular regulated kinases (ERK) and epidermal growth factor receptor (EGFR), inactivation of phosphatase and tensin homolog (PTEN) and the ALK mutation in lung cancer." (PMID 28122336, 2017). "Crizotinib, an oral, selective, small-molecule ALK inhibitor, showed impressive clinical activity in patients with lung cancer associated with ALK rearrangement, leading to approval for clinical use in 2013." (PMID 28938595, 2017). "Non-small cell lung cancer (NSCLC) causes approximately 80–85% of lung cancer deaths and mutations associated with the anaplastic lymphoma kinase (ALK) gene occur in 3–8% of lung cancer patients." (PMID 29066738, 2017). "The Vysis LSI ALK Break Apart FISH Probe Kit has been approved by the FDA as a companion diagnostic test for administration of ALK inhibitors in lung cancer patients." (PMID 28970558, 2017). "For example, mutated BRAF is seen in melanomas, ALK raises suspicion for lung cancer, and EGFR has been described in multiple cancer types including lung, colorectal, pancreatic, breast, and thyroid." (PMID 28054963, 2017). "Recent data have suggested that ALK rearrangement lung cancers are associated with a younger age at diagnosis." (PMID 27191886, 2016). "Epidermal growth factors receptor (EGFR) common mutations first and anaplastic lymphoma kinase (ALK) translocations later led new insights in lung cancer biology knowledge." (PMID 27433281, 2016). "Epidermal growth factor receptor (EGFR) mutations and anaplastic lymphoma kinase (ALK) fusion genes represent novel oncogenes that are associated with non–small-cell lung cancers (NSCLC)." (PMID 27322143, 2016). "Recently, activation of the anaplastic lymphoma kinase (ALK) gene in lung cancer by fusion to echinoderm microtubule-associated protein-like 4 (EML4) or other gene partners (such as BIRC6, TFG, KIF5B and KLC1) has been identified as oncogenic events." (PMID 26789109, 2016). "Molecular testing of EGFR and ALK in lung adenocarcinoma is recommended by the guidelines from College of American Pathologists, the International Association for the Study of Lung Cancer, and the Association for Molecular Pathology." (PMID 26992209, 2016).